LTBP3 (latent transforming growth factor beta binding protein 3)
Description:
Key regulator of transforming growth factor beta (TGFB1, TGFB2 and TGFB3) that controls TGF-beta activation by maintaining it in a latent state during storage in extracellular space. Associates specifically via disulfide bonds with the Latency-associated peptide (LAP), which is the regulatory chain of TGF-beta, and regulates integrin-dependent activation of TGF-beta.
Synonyms: LTBP-3; DASS; GPHYSD3; LTBP2; STHAG6; pp6425
Tractability: Antibody: UniProt places it where antibodies can reach, with high confidence; its Gene Ontology location is reachable by antibodies, with high confidence; UniProt predicts a signal peptide or a membrane-spanning region. PROTAC: ubiquitination databases record sites on it.
Gene: Protein-coding gene on chromosome 11 (65,538,559 to 65,558,930, reverse strand). Ensembl gene ENSG00000168056.
Subcellular location: Secreted; Secreted, extracellular space, extracellular matrix
Pathways (Reactome):
Extracellular matrix organization: Molecules associated with elastic fibres
Signal Transduction: TGF-beta receptor signaling activates SMADs
Gene Ontology:
Molecular function: protein binding; transforming growth factor beta binding; calcium ion binding
Biological process: positive regulation of mesenchymal stem cell differentiation; positive regulation of mesenchymal stem cell proliferation; transforming growth factor beta receptor signaling pathway; regulation of cell differentiation
Cellular component: extracellular exosome; extracellular matrix; extracellular region; elastic fiber; non-collagenous component of interstitial matrix; transforming growth factor beta complex; microfibril
Genetic constraint (gnomAD): Loss-of-function variants: 99 observed, 141.95 expected, observed/expected ratio (o/e) 0.7, 90% interval 0.59 to 0.82. The upper end of that interval is the gene's LOEUF score, 0.82, which puts it in group 3 of 6, group 1 being the genes least tolerant of losing a copy. Missense variants: 1,583 observed, 1,684.1 expected, observed/expected ratio (o/e) 0.94, 90% interval 0.9 to 0.98. Synonymous variants: 822 observed, 717.43 expected, observed/expected ratio (o/e) 1.15, 90% interval 1.08 to 1.21.
Homologues: Orthologues: chimpanzee LTBP3 (99% identical), dog LTBP3 (96% identical), pig LTBP3 (96% identical), rat Ltbp3 (94% identical), mouse Ltbp3 (91% identical), macaque LTBP3 (84% identical), guinea pig LTBP3 (70% identical), zebrafish ltbp3 (49% identical). Paralogues in human: LTBP1 (40% identical), LTBP2 (36% identical), LTBP4 (33% identical).
Diseases named in the same sentence as LTBP3 in open-access papers:
LTBP3 is named in the same sentence as 72 diseases in open-access papers, as found by Europe PMC text mining. Sharing a sentence is not in itself a finding about the gene and the disease. The quoted sentences say what the papers report.
myeloma (8 papers, 2016 to 2022). "Some studies are demonstrating that LTBP3 is also associated with a wide range of diseases, such as hepatocellular carcinoma, multiple myeloma, and oligodontia." (PMID 36123690, 2022). "LncRNA MALATl can bind to the promoters of Spl and LTBP3 to promote the expression of LTBP3 and maintain myeloma-derived mesenchymal stem cell activity." (PMID 33176682, 2020). "MALAT1 in another hematological cancer, multiple myeloma (MM) has been shown to also target latent transforming growth factor beta-binding protein 3 (LTB3) and suggest that MALAT1 may have widespread effects across different transcription complexes." (PMID 27998273, 2016). "Knockdown of MALAT1 inhibits LTBP3 transcription and TGF-β secretion in MSCs from the bone marrow of myeloma patients, whereas overexpression of MALAT1 increases LTBP3 transcription and TGF-β secretion in MSCs from healthy donors." (PMID 31717266, 2019). "In multiple myeloma cells, lncRNA MALAT1 transcript activates LTBP3-regulated molecules in tumor suppressor and oncogenic pathways." (PMID 27090737, 2016). "More specifically, MALAT1, expressed at high levels in the MSCs from myeloma patients, was shown to recruit the transcription factor SP1 on the LTBP3 promoter contributing to the increase of LTBP3 expression, most likely by stabilizing the interaction between SP1 and SP1-consensus sequences." (PMID 27177333, 2016). "MALAT-1 has been reported to activate the transcription of latent-transforming growth factor beta-binding protein 3 (LTBP3), a transforming growth factor beta (TGF-β) bioactivity-regulating gene, by recruiting transcription factor Sp1 to the LTBP3 promoter in MSCs from myeloma patients." (PMID 28951743, 2017).
geleophysic dysplasia (5 papers, 2019 to 2026). Geleophysic dysplasia is a rare skeletal dysplasia characterized by short stature, prominent abnormalities in hands and feet, and a characteristic facial appearance (described as "happy''). "The aim of this study is to investigate the de novo mutation and clinical features of latent transforming growth factor-beta-binding protein 3 (LTBP3) gene-associated geleophysic dysplasia 3, and possible mechanisms of action." (PMID 39705488, 2024). "In humans, the heterozygous variants in LTBP3 cause geleophysic dysplasia and acromicric dysplasia, while the homozygous variants are associated with amelogenesis imperfecta and short stature." (PMID 37548766, 2023). "Geleophysic dysplasia (GD) is caused by recessive mutations in ADAMTSL2 (a disintegrin and metalloprotease with thrombospondin type I motifs-2; GD1), or dominant mutations in FBN1 (GD2) or LTBP3 (GD3)." (PMID 41864337, 2026). "Monoallelic variants in LTBP3 lead to ACMICD and geleophysic dysplasia, resulting in a disproportionate short stature with a short trunk, distinctive facial features, and heart diseases, and an increased susceptibility to thoracic aortic aneurysms and dissections." (PMID 37548766, 2023).
thoracic aortic aneurysm (5 papers, 2019 to 2025). An aneurysm formed in the wall of the proximal portion of the descending aorta proceeding from the arch of the aorta. "Mutations in LTBP3 cause dental anomalies and short stature but also appear to increase risk of thoracic aortic aneurysms and dissections." (PMID 30926607, 2019). "Notably, preliminary reports have also linked heterozygous variants in LTBP3 to thoracic aortic aneurysm and dissection in autosomal dominant contexts, suggesting that LTBP3 may play a more direct and clinically relevant role in aortic pathology than previously appreciated." (PMID 40981152, 2025). "The role of LTBP3-TGF-β signaling in the differentiation of cardiac progenitor cells and formation of the heart has been researched; besides, the LTBP3 pathogenic variants are reported to predispose individuals to thoracic aortic aneurysms and aortic dissections." (PMID 37754271, 2023).
aneurysm (4 papers, 2019 to 2022). Bulging or ballooning in an area of an artery secondary to arterial wall weakening. "In 2018, Guo and colleagues reported that pathogenic variants in LTBP3 segregated with aneurysms of the aortic root and/or ascending aorta and aortic dissections in two families." (PMID 35098309, 2022). "Patients carrying LTBP3 (Latent TGFβ-binding protein 3) variants present aneurysms and dissections of the thoracic aorta, as well as aneurysms of the abdominal aorta and other arteries." (PMID 34912367, 2021). "Additionally, individuals with compound heterozygous or homozygous variants in LTBP3, the gene encoding latent TGF-β binding protein 3 (LTBP3), suffer from aneurysms and dissections of the thoracic aorta and other arteries." (PMID 33514025, 2021). "Aberrant LTBP-3-TGFβ complexes may be responsible for aortic dilation and dissection in MFS as MFS mice lacking LTBP-3 had fewer aneurysms and less fragmented elastic fibres." (PMID 30016650, 2019).
amelogenesis imperfecta (2 papers, 2021 to 2023). Amelogenesis imperfecta (AI) represents a group of developmental conditions affecting the structure and clinical appearance of the enamel of all or nearly all the teeth in a more or less equal manner, and which may be associated with morphologic or biochemical changes elsewhere in the body. "On the other hand, biallelic variants in LTBP3 cause dental anomalies (amelogenesis imperfecta) and short stature." (PMID 37548766, 2023). "We here report a young boy born from consanguineous parents with a complex phenotype including skeletal dysplasia associated with aortic stenosis, hypertrophic cardiomyopathy, hypodontia and amelogenesis imperfecta caused by a previously unreported homozygous LTBP3 splice site variant." (PMID 34573388, 2021). "This work provides further evidence that brachyolmia with amelogenesis imperfecta is a distinct nosologic entity and that variations in LTBP3 are involved in its pathogenesis." (PMID 34573388, 2021).
Aortic dissection (2 papers, 2021 to 2023). Aortic dissection refers to a tear in the intimal layer of the aorta causing a separation between the intima and the medial layers of the aorta. "Our study identified two compound heterozygous variants in LTBP3 in an aortic dissection patient, along with short stature and dental problems." (PMID 34906192, 2021). "In summary, we identified the first case of a TAAD patient with bi-allelic LTBP3 frameshift mutations in an Asian population, as well as several rare LTBP3 variants in affected individuals with early aortic dissection." (PMID 34906192, 2021). "The relationship between rare LTBP3 heterozygous variants and aortic dissection risk also remains unclear." (PMID 34906192, 2021).
brachyolmia (2 papers, 2015 to 2021). Brachyolmia is a rare, clinically and genetically heterogeneous group of bone disorders characterized by short trunk, mild short stature, scoliosis and generalized platyspondyly without significant abnormalities in the long bones. "In conclusion, the present finding further supports the evidence that inactivating biallelic LTBP3 variants are responsible for a very rare, autosomal recessive disorder, named brachyolmia with AI." (PMID 34573388, 2021). "More recently, pathogenic variants in LTBP3 have been found to be implicated in the pathogenesis of brachyolmia-AI in a small number of unrelated families." (PMID 34573388, 2021). "In this study, we report on a patient with brachyolmia-AI caused by a novel homozygous inactivating variant in LTBP3." (PMID 34573388, 2021). "Biallelic variants in LTBP3 have previously been reported in brachyolmia-AI, the majority representing frameshift and nonsense variants." (PMID 34573388, 2021). "Mutation in the latent transforming growth factor (TGF)-beta binding protein 3 (LTBP3) gene causes brachyolmia with amelogenesis imperfecta." (PMID 26511208, 2015). "We report on an affected boy, born from consanguineous parents with negative family history, showing DASS phenotype (brachyolmia with AI, hereafter) associated to a previously unreported homozygous splicing variant (c.2894-2A>G) in the LTBP3 gene." (PMID 34573388, 2021). "Indeed, recent studies demonstrated that pathogenic variants in the latent transforming growth factor (TGF)-β binding protein 3 gene (LTBP3, 11q13.1, OMIM *602090) are responsible for brachyolmia with different teeth disorders." (PMID 34573388, 2021).
breast carcinoma (2 papers, 2014 to 2023). "We showed that LTBP3 and SNED1, identified by proteomics in our study as differentially expressed between poorly and highly metastatic mammary tumors, correlate at the transcript level with clinical outcome in a cohort of ER−/PR− breast cancer patient." (PMID 24618895, 2014). "Importantly, we further demonstrated that the level of expression of LTBP3 and SNED1 negatively correlated with breast cancer patient prognosis." (PMID 36918099, 2023). "In addition, we show that Ltbp3 and Sned1 mRNAs are up-regulated during malignant progression in the autochthonous MMTV-PyMT murine mammary tumor model." (PMID 24618895, 2014). "While expression levels for SNED1 and LTBP3 were not significantly correlated across all mammary cancer sub-types, they were significantly correlated (p values of 0.0079 and 0.034, respectively) with poor prognosis for estrogen-receptor-negative and progesterone-receptor-negative (ER−/PR−) patients." (PMID 24618895, 2014).
dysplasia (2 papers, 2021). A usually neoplastic transformation of the cell, associated with altered architectural tissue patterns. "Other LTBP3 variants cause an autosomal dominant phenotype in humans, termed geleophysic dysplasia 3 (GPHYSD3, OMIM #617809)." (PMID 34946872, 2021). "Notably, pathogenic variations in LTBP3 have also been associated with acromic dysplasia (ACMICD, OMIM #102370) and geleophysic dysplasia 3 (GPHYSD3, OMIM #617809)." (PMID 34573388, 2021).
Hypodontia (2 papers, 2015 to 2021). The absence of five or less teeth from the normal series by a failure to develop. "The occurrence of hypodontia cannot be considered as sufficient for a diagnosis of hypohydrotic ectodermal dysplasia and represents a key feature in patients with pathogenic biallelic LTBP3 variants." (PMID 34573388, 2021). "We cannot exclude a potential role of EDA variant in the etiopathogenesis of hypodontia in our patient, but without a positive family history and with his mother being healthy, it appears more likely that the dental anomalies, along with other symptoms, were caused by LTBP3 variant." (PMID 34573388, 2021).
AIDS (1 paper, 2022). A syndrome resulting from the acquired deficiency of cellular immunity caused by the human immunodeficiency virus (HIV). "We screened four immune cell-related genes, ARRB1, DPEP2, LTBP3, and RGCC, which may be considered as the diagnostic markers for HIV-1/AIDS." (PMID 36123690, 2022).
alopecia (1 paper, 2022). Hair loss usually from the scalp. "For example, the CCDC41 gene variants would be present in nephronophthisis; LSS gene variants can result in alopecia; LTBP3 gene variants are characterized by hypoplastic amelogenesis imperfecta; NTRK1 gene variants have been found to cause congenital insensitivity to pain." (PMID 35911831, 2022).
aneurysmal disease (1 paper, 2022). "In summary, although mutations in LTBP3 have been linked to human aneurysmal disease, the causality of deletions involving the LTBP1 locus remains speculative." (PMID 35098309, 2022).
Aortic root aneurysm (1 paper, 2022). An abnormal localized widening (dilatation) of the aortic root. "Human relevance is supported by recent studies implicating genetic lesions in LTBP3 and, potentially, LTBP1 as heritable causes of aortic root aneurysm." (PMID 35098309, 2022).
breast tumors (1 paper, 2014). "As demonstrated for SNED1 and LTBP3, other proteins that are part of the proteomic signatures of highly and poorly metastatic breast tumors described here, may prove to correlate with patient outcomes and may prove useful as novel prognostic and diagnostic biomarkers." (PMID 24618895, 2014).
colorectal tumour (1 paper, 2019). "Kaplan Meier survival curve showed the expression of HLAB, 14-3-3β, ADAMTS2, LTBP3, NME2 and JAG2 on colorectal tumour cells associated with CRC specific survival." (PMID 30679934, 2019).
depression (1 paper, 2025). "Eight SNPs corresponding to six protein-coding genes (TNXB, NCAM1, LTBP3, BTN3A2, DAG1, FHIT) were identified that were highly associated with depression." (PMID 39897774, 2025). "Our findings confirmed previous evidence for TNXB- and NCAM1 in the pathophysiology of depression and suggested new potential candidate genes (LTBP3, BTN3A2, DAG1 and FHIT) that warrant further investigation." (PMID 39897774, 2025). "The present study identified six protein-coding genes associated with depression and primarily involved in inflammation (TNXB), neuroplasticity (NCAM1 and LTBP3), immune response (BTN3A2), cell survival (DAG1) and circadian clock modification (FHIT)." (PMID 39897774, 2025). "Our findings confirmed previous evidence for TNXB- and NCAM1 in the pathophysiology of depression and suggested four new potential candidate genes (LTBP3, BTN3A2, DAG1 and FHIT) that warrant further investigation." (PMID 39897774, 2025). "We have identified six protein-coding genes associated with depression and primarily involved in inflammation (TNXB), neuroplasticity (NCAM1 and LTBP3), immune response (BTN3A2), cell survival (DAG1) and circadian clock modification (FHIT)." (PMID 39897774, 2025). "Other potential candidate genes whose function might provide new insights in the pathophysiological process of depression include LTBP3, BTN3A2, DAG1 and FHIT." (PMID 39897774, 2025).
epilepsy (1 paper, 2025). A brain disorder characterized by episodes of abnormally increased neuronal discharge resulting in transient episodes of sensory or motor neurological dysfunction, or psychic dysfunction. "We analyzed OLINK proteomics data from a large epilepsy cohort in which we have previously found four differentially expressed proteins (CDH15, PAEP, LTBP3, PHOSPHO1)." (PMID 40591616, 2025).
geleophysic dysplasia type 2 (1 paper, 2024). "The same phenotype can be caused by monoallelic variants in FBN1 (encoding fibrillin 1) or LTBP3 (encoding latent transforming growth factor-beta-binding protein 3), which are referred to as geleophysic dysplasia type 2 (GD2) and type 3 (GD3), respectively." (PMID 38300707, 2024).
glaucoma (1 paper, 2025). Increased pressure in the eyeball due to obstruction of the outflow of aqueous humor. "In the context of glaucoma, LTBP3 contributes to extracellular matrix remodeling, while mutations in LTBP1 have been identified in clinical families with AD." (PMID 40988281, 2025). "Among them, GADD45B, FZD1, EFNA1, LTBP3, and CST3 have been reported to potentially play a role in the development of both AD and glaucoma." (PMID 40988281, 2025).
HIV-1 infection (1 paper, 2022). The type species of lentivirus and the etiologic agent of acquired immunodeficiency syndrome (AIDS). "In addition, RGCC was shown to be involved in the negative regulation of fibroblast growth factor synthesis, and both RGCC and LTBP3 have been connected to the regulation of extracellular matrix formation (GO: 0,085,029) during HIV-1 infection." (PMID 36123690, 2022). "As the best model for diagnosing HIV-1±, RF was used to select four critical immune cell-related genes, namely, ARRB1, DPEP2, LTBP3, and RGCC, and a nomogram model was created to predict the occurrence of HIV-1 infection based on four key immune cell-related genes." (PMID 36123690, 2022).
lung carcinoma (1 paper, 2011). "In human lung cancer CL1-5 cells, ACVR1B (1.5-fold) and ID1 (inhibitor of DNA binding 1, dominant negative helix-loop-helix protein, 1.3-fold) were observed to be up-regulated, while LTBP3 (latent TGF-β binding protein 3, 1/1.6-fold) was down-regulated." (PMID 21998723, 2011).
Marfan syndrome (1 paper, 2023). A disorder of the connective tissue. "A study on a mouse model of Marfan syndrome showed that Ltbp-3 deficiency was linked to reduced TGFB signaling, less aortic damage and increased survival, suggesting that TGFB signaling is involved in the progression of the aortic disease." (PMID 37238945, 2023).
osteoarthritis (1 paper, 2012). A noninflammatory degenerative joint disease occurring chiefly in older persons, characterized by degeneration of the articular cartilage, hypertrophy of bone at the margins and changes in the synovial membrane. "Interestingly, LTBP-3 null mice demonstrate altered skull development, osteoarthritis and osteopetrosis, defects that phenocopy those observed in animals with impaired TGFβ signaling in osteoblasts." (PMID 22238668, 2012).
osteopetrosis (1 paper, 2012). Osteopetrosis, also known as marble bone disease, is a descriptive term that refers to a group of rare, heritable disorders of the skeleton characterized by increased bone density on radiographs. "Interestingly, of the LTBP proteins, only LTBP-3 has been implicated in bone development since LTBP-3 null mice display a distinct cranial phenotype and develop osteopetrosis." (PMID 22238668, 2012).